IGKJ4 (immunoglobulin kappa joining 4)
Synonyms: J4
Gene: Immunoglobulin joining (J) gene on chromosome 2 (88,860,886 to 88,860,922, reverse strand). Ensembl gene ENSG00000211594.
Diseases named in the same sentence as IGKJ4 in open-access papers:
IGKJ4 is named in the same sentence as 8 diseases in open-access papers, as found by Europe PMC text mining. Sharing a sentence is not in itself a finding about the gene and the disease.
IGKJ4 shares sentences with these, for which no sentence is quoted: Alzheimer disease (1 paper); brainstem glioma (1); cancer (1); medulloblastoma (1); osteosarcoma (1); skin tumors (1); T-cell acute lymphoblastic leukemia (1); tumor (1).